ATG5 (autophagy related 5)
Diseases named in the same sentence as ATG5 in open-access papers (continued):
Sharing a sentence is not in itself a finding about the gene and the disease.
neuroblastoma (19 papers, 2014 to 2024). Neuroblastoma (NB) is the most common solid, extracranial childhood tumor. "Glod4 gene in mouse neuroblastoma N2a-APPswe cells was silenced by RNA interference and Glod4, Aβ precursor protein (Aβpp), Atg5, p62, and Lc3 proteins and mRNAs were quantified." (PMID 39302370, 2024). "A study conducted on neuroblastoma cells revealed that overexpression of ATG5 or beclin-1 reduced angiogenesis, while silencing of ATG5 and Beclin-1 had the opposite effect." (PMID 38576024, 2024). "Inhibition of ATG5-dependent autophagy through overexpression of a dominant negative form of ATG5 (dnATG5) in a neuroblastoma cell line increases cell death induced by paraquat or MPP+." (PMID 37887330, 2023). "Chloroquine has been shown to decrease proteolysis in human neuroblastoma SK-N-SH cells and in WT or Atg5−/− mouse embryonic fibroblasts." (PMID 35609021, 2022). "It has previously been stated that the natural compound 18α-glycyrrhetinic acid and OxyR-mediated autophagy display accumulation of Atg5, Atg7, and Beclin-1 in neuroblastoma cells." (PMID 33800526, 2021). "SNHG16 promoted proliferation, migration, invasion, and autophagy of neuroblastoma cells through sponging miR-542-3p and upregulating autophagy-related gene 5 (ATG5)." (PMID 32964050, 2020). "Downregulation of Atg5 or Beclin1 in human neuroblastoma cells M17 lead to α‐syn aggregations." (PMID 37668106, 2023). "SNHG16 could inhibit the expression of miR-542-3p and upregulate the autophagy related gene 5 (ATG5) to foster proliferation, migration, invasion, and autophagy of neuroblastoma." (PMID 39279987, 2022). "While ABT-199 successfully induces apoptosis in high BCL2-expressing neuroblastoma SHSY-5Y cells, BAU-243 triggered autophagic cell death rather than apoptosis in GBM A172 cells, indicated by the upregulation of BECN1, ATG5, and MAP1LC3B expression." (PMID 36309485, 2022). "The expression of LC3B and ATG3, ATG5, ATG7, ATG12 proteins was also markedly up-regulated after BIX01294 treatment in neuroblastoma cells." (PMID 27934912, 2016). "Colocalization of ATG5- and LAMP1-positive endomembranes was also seen in H4 (neuroblastoma) and HCT116 cells." (PMID 25254627, 2014). "Protein levels of the autophagy marker ATG5 significantly increased after 24 h RF exposures in neuroblastoma cells but not in N9 cells, evidencing the dependency of the effect on cell type and exposure duration." (PMID 35955556, 2022). "The autophagy pathway plays a significant role in dioscin-mediated neuroprotection on SH-SY5Y neuroblastoma cells, but several limitations of this study need to be overcome by future studies, including in MPTP-intoxicated, trans-genic and autophagy impaired (ATG5-/-) animals." (PMID 35566180, 2022).
leukemia (18 papers, 2015 to 2026). A malignant (clonal) hematologic disorder, involving hematopoietic stem cells and characterized by the presence of primitive or atypical myeloid or lymphoid cells in the bone marrow and the blood. "For example, an in vivo model with heterozygous loss of Atg5 exhibits a glycolytic shift and aggressive leukemia, suggesting autophagic control of glycolysis in leukemic transformation." (PMID 35526025, 2022). "In line with this, Atg5 loss accelerates MLL-ENL induced leukemia in a mice model." (PMID 41275290, 2025). "However, it has been reported that the heterozygous knockout of Atg5 shortens survival in a mouse leukemia model caused by MLL::ENL." (PMID 39596291, 2024). "Furthermore, this study showed that heterozygous loss of Atg5 or Atg7 in a MLL-ENL AML mouse model led to more aggressive leukemia progression, suggesting a tumor-suppressive role for autophagy." (PMID 30678185, 2019). "Depletion of autophagy gene ATG5 led to increased proliferation and more aggressive leukemia in the MLL-ENL-induced murine AML model." (PMID 40066097, 2025). "Mutations in ATGs, such as ATG2B, ATG5, ATG7, ATG9B, and ATG12, have been linked to frameshift mutations in leukemias but also gastrointestinal and liver cancers, highlighting their significance in cancer biology." (PMID 40227235, 2025). "In the mixed lineage leukemia–eleven nineteen leukemia-induced AML model, the role of autophagy in leukemia-initiating cells (LICs) was analyzed by the loss of Atg5 or Atg7." (PMID 39596291, 2024). "In contrast, genetic inhibition of murine Atg5 and Atg7 can prolong leukemia survival and delay the elimination of leukemia-initiating cells." (PMID 37180758, 2023). "The heterozygous deletion of ATG5 leads to increased proliferation in vitro and more aggressive leukemias in an MLL-ENL “in vivo” model of AML." (PMID 37296673, 2023). "It was shown that loss of the core autophagy genes ATG5 and ATG7 induced apoptosis and decreased leukemia progression in a murine leukemia model." (PMID 34885250, 2021). "Conversely, another study on MLL-ENL leukemic mice showed that homozygous deletion of Atg5 or Atg7 in bone marrow cells reduced the frequency of leukemia-initiating cells (LICs) and decelerated leukemia progression." (PMID 34462526, 2021). "Members within this cascade such as ATG4B, ATG7, and ATG5 not only show dysregulation in leukemia, but can also be effectively targeted to halt the autophagy process, thus, making interruption of autophagosome maturation an attractive area of study." (PMID 30678185, 2019). "In contrast, in our model using MLL-AF9-driven leukemia with homozygous Atg5 deletion, we detected a transient decrease in colony-formation potential during leukemia initiation and no significant LSC cell death hereafter." (PMID 27607576, 2016). "Furthermore, we found that the autophagy inhibition through knockout of ATG5 in KrasG12D/+ mutant mice promoted the expansion of HSPCs and inhibited the progression of leukemia disease, consistent with the phenotypes of knockout of METTL14." (PMID 40819104, 2026). "Similarly, Atg5/7 is required for the maintenance of leukemia-initiating cells in murine myeloid leukemia." (PMID 41275290, 2025). "The expression of proteins related to apoptosis and autophagy, including cleaved-PARP-1, Bcl-2, Bax, LC3-I/II, Beclin-1, Atg5, p62, phospho-AMPK, AMPK, phospho-mTOR, mTOR, phospho-Akt, and Akt, in human leukemia cells were evaluated using Western blotting." (PMID 36826047, 2023). "Heterozygous deletion of Atg5 in Mixed Lineage Leukemia-Eleven Nineteen Leukemia (MLL-ENL) induced murine HSCs led to a higher proliferation rate and a more aggressive leukemia in vivo due to a shift towards glycolytic metabolism." (PMID 34462526, 2021). "In addition, inhibition of autophagy, followed by deletion of ATG5 or ATG7, reduces leukemia-initiating cells (LICs) and increases mitochondrial ROS." (PMID 40066097, 2025).
leukemia (continued). "Atg5 plays roles in MLL-AF9 AML initiation but not in the secondary transplanted leukemia stem cells." (PMID 38490977, 2024). "Another study demonstrated that ATG5 participates in the development of MLL-AF9-driven leukemia, but not in AML-sensitive chemotherapy mice expressing MLL-AF9." (PMID 37296673, 2023). "Another study showed that ATG5 contributes to the development of MLL-AF9-driven leukemia, but not in chemotherapeutically sensitive mice with AML expressing MLL-AF9." (PMID 35526025, 2022). "Importantly, autophagy-related proteins (ATG) including ATG5 and ATG7, which are well known critical autophagy genes, have been reported to promote cell proliferation in leukemia." (PMID 34885250, 2021). "We previously reported that Atg5-specific siRNA treatment and autophagosome formation inhibitors, MRT and SBI-0206965 (SBI), but not an autolysosome inhibitor, hydroxychloroquine, induced accumulation of cytosolic DNA fragments preferentially in leukemia cells." (PMID 38466568, 2024). "Consistent with a transient decrease in colony-forming potential in vitro, the in vivo deletion of Atg5 in MLL-AF9-transduced bone marrow cells during primary transplantation prolonged the survival of recipient mice, suggesting that autophagy has a role in MLL-AF9-driven leukemia initiation." (PMID 27607576, 2016). "At a time point at which 0/10 mice injected with the Atg5 WT ENL–MLL lines had neither developed clinical symptoms nor signs of leukemia, 10/10 mice injected with HET Atg5 MLL–ENL lines had to be killed because of typical leukemic clinical symptoms." (PMID 26568842, 2015).
renal fibrosis (17 papers, 2018 to 2024). A final common manifestation of a wide variety of chronic kidney diseases characterized by glomerulosclerosis and tubulointerstitial fibrosis. "Subsequently, the protective role of spermine supplementation was disrupted in ATG5‐deficient mice, which in part indicates that ATG5‐mediated autophagy is required for the protective effects of spermine against renal fibrosis." (PMID 38775007, 2024). "This Atg5-mediated autophagy deficiency in proximal tubules promotes the cell cycle G2/M arrest and leads to renal fibrosis." (PMID 30717078, 2019). "Therefore, our study confirmed that Atg5 deficiency promoted the conversion of macrophages to an antifibrotic phenotype, consequently alleviating renal fibrosis." (PMID 38594728, 2024). "Collectively, the results indicate that Atg5 deletion in proximal tubule aggravates renal injury during the acute phase while attenuating renal fibrosis during the recovery period following AKI." (PMID 39639205, 2024). "To further verify the effect of Atg5 in renal proximal tubules on renal fibrosis, we established a UUO model by ligating the left ureter, a classic model for studying renal interstitial fibrosis." (PMID 39639205, 2024). "Collectively, these results indicate that the SMOX/spermine axis coordinates ATG5‐mediated autophagy to orchestrate renal fibrosis." (PMID 38775007, 2024). "Our in vivo and in vitro results revealed that ATG5 knockdown aggravated a decrease in spermine during renal fibrosis." (PMID 38775007, 2024). "We performed unilateral renal ischemia surgery (duration, 31 min) to elucidate the specific role of Atg5 in macrophages in the progression of renal fibrosis." (PMID 38594728, 2024). "In summary, this study revealed that specific deletion of Atg5 in myeloid cells protects against renal fibrosis development by attenuating macrophage migration into the injured kidney." (PMID 38594728, 2024). "The deficiency of the ATG5 gene also led to increased collagen type 1(COL1) production, further promoting renal fibrosis in AGT II-stimulated primary proximal tubular cells." (PMID 38099142, 2023). "Although both studies tested Atg5 knockout mice, they examined renal fibrosis in different disease models." (PMID 35707397, 2022). "We previously showed that ATG5-mediated autophagy in proximal TECs attenuated G2/M cell cycle arrest and renal fibrosis." (PMID 30874544, 2019). "ATG5-mediated autophagy in proximal TECs has recently been shown to protect against G2/M cell cycle arrest and renal fibrosis." (PMID 30874544, 2019). "In the present study, we demonstrated that the role of autophagy-related protein 5 (ATG5) in cell-autonomous defense against renal inflammation is autophagy-dependent in a model of renal fibrosis induced by unilateral ureteric obstruction (UUO)." (PMID 30874544, 2019). "Intriguingly, a previous study clarified that autophagy plays a pivotal role in regulating cell cycle arrest of proximal epithelial cells, and that enhanced expression of Atg5 could suppress renal fibrosis by rescuing G2/M arrest." (PMID 38789954, 2024). "We further explored whether deletion of myeloid Atg5 impacts recovery from renal ischemic injury and promotes subsequent renal fibrosis." (PMID 38594728, 2024). "Our results showed that Atg5 is profibrotic in renal fibrosis induced by AKI and UUO." (PMID 39639205, 2024). "In mice with unilateral ureteral obstruction (UUO), rapamycin treatment attenuated the tubulointerstitial fibrosis, however, proximal tubular epithelial cell-specific deletion of Atg5 abolished the protective effects of rapamycin and exacerbated renal fibrosis." (PMID 29731718, 2018). "In our study, although Atg5 deficiency in the proximal tubules exacerbates acute renal injury, the feedback regulation mechanism of ROS rapidly restores early injury to control levels without affecting the improvement of renal fibrosis during the repair phase." (PMID 39639205, 2024).
renal fibrosis (continued). "With the use of conditional autophagy-related genes (ATGs), such as Atg5 or Atg7, knockout mice, accompanied by the construction of animal disease models and the improvement of methods for monitoring autophagy, future research on autophagy in renal fibrosis will be further elucidated." (PMID 35656109, 2022). "Contrariwise, similar experiments in mice with the conditional deletion of autophagy related 5 (ATG5) resulted in increased interstitial fibrosis, and rapamycin (a pharmacologic inducer of autophagy) reduced the unilateral ureteral obstruction stimulated renal fibrosis." (PMID 30717078, 2019). "In this study, MPs increased the levels of Cd-mediated autophagy marker LC3-II and the autophagy early proteins ATG5, Beclin-1, and ATG7 and increased the levels of the renal fibrosis marker proteins α-SMA, TGF-β1, and COL4A1." (PMID 36430889, 2022). "The increases of serum BUN, Scr, renal fibrosis-related genes and proteins (Vimentin, α-SMA, and TGF-β1), and autophagy-related genes and proteins, (ATG5 and LC3II) were inhibited in TLR4−/− mice." (PMID 32108135, 2020). "This study showed that Atg5 deletion in myeloid cells did not affect renal function in the early stages following mild ischemic injury but inhibited renal fibrosis development after severe AKI." (PMID 38594728, 2024). "Moreover, the interplay between autophagy protein 5 (ATG5) and SMOX plays a crucial role in regulating the progression of renal fibrosis by preserving intracellular spermine levels." (PMID 38775007, 2024). "Furthermore, we demonstrated that ATG5 physically interacted with SMOX to modulate the occurrence and development of renal fibrosis through maintaining intracellular spermine levels." (PMID 38775007, 2024). "And the ATG5/SMOX interaction may be involved in the occurrence and development of renal fibrosis through regulating spermine content." (PMID 38775007, 2024).
diabetes (16 papers, 2013 to 2025). "tRF-Gly-CCC-039 associates with diabetes foot sustained healing, while tRF-5014a inhibits autophagy-linked ATG5 in diabetic cardiomyopathy (DCM)." (PMID 38596214, 2024). "Autophagy is a cellular degradation-recycling system for aggregated proteins and damaged organelles, and its dysregulation characterized in Atg5 or Atg7-deifient mice is implicated in various age-related diseases including neurodegeneration, diabetes, and hepatocarcinoma." (PMID 24260490, 2013). "Diabetes induction also decreased the expressions of ATG-5 as a component of the ubiquitin-like conjugation system and accordingly diminished the elongation of the phagophore membrane, leading to the limitation of the formation of autophagosomes." (PMID 36841820, 2023). "Mechanism studies revealed that exogenous H2S inhibited diabetes-induced autophagy through decreasing the number of autophagosomes and the expression levels of Beclin-1, Atg3, Atg5 and Atg16." (PMID 34201520, 2021). "Quantification of these proteins revealed an increase in both Atg5 and Beclin-1 in the retinas of diabetic mice compared to control (P = 0.03 and 0.006, respectively, 12 weeks after diabetes induction, t-test)." (PMID 26924963, 2016). "However, at 22 weeks post diabetes, glomerular Atg5 and Becn1 were regulated differently indicating another mode of regulation for these genes." (PMID 29725042, 2018). "For instance, ATG5 and LC3B are found to be decreased in diabetes mellitus patients with or without complications, indicating that downregulated ATG5 and LC3B may be implicated in the deficiencies of autophagy." (PMID 37223013, 2023). "In detail, STZ-induced diabetes remarkably reduced the expression of ATG-1, ATG-5, Beclin-1, and LAMP-2." (PMID 36841820, 2023). "Atg5 and LAMP2 were highly expressed in control mice, and both diabetes and I/R alone resulted in LAMP2 and Atg5 reduction." (PMID 36562207, 2023). "In line with previous studies, we found that diabetes was characterized by lower expression of autophagy indicators in db/db mice livers, demonstrated by lower expression levels of LC3 and ATG5 proteins." (PMID 32194395, 2020). "In the current study, we found that diabetes significantly increased autophagic activation, as evidenced by the upregulation in the expression of LC3B-II, ATG5, and ATG7 and the downregulation of P62 in the hippocampus." (PMID 31788335, 2019). "Podocyte-specific deletion of Atg5 promoted diabetes-induced glomerulopathy in murine models of T1DM14 and T2DM15, indicating that autophagy in the podocyte counteracts metabolic stress by diabetes." (PMID 28706237, 2017). "As autophagy is also strongly suggested to be associated with the pathogenesis of metabolic diseases including diabetes, the interaction between CDKAL1 and ATG5 could exist." (PMID 26509176, 2015).
glomerulosclerosis (16 papers, 2015 to 2025). A hardening of the kidney glomerulus caused by scarring of the blood vessels. "In aging mice, Atg5 gene deletion in podocyte resulted in podocyte loss and the development of glomerulosclerosis." (PMID 38099142, 2023). "Compared with control mice, the podocyte autophagy-deficient mice (specifically deletion of Atg5 in podocytes) showed an accelerated diabetes-induced podocytopathy, manifested as massive proteinuria and glomerulosclerosis." (PMID 35656109, 2022). "Firstly, a study on PcKO mice, the Atg5 gene (functional block of autophagy) was associated with slow progression of podocyte degeneration and then to glomerulosclerosis." (PMID 30333281, 2019). "Hartleben and colleagues elegantly demonstrated that podocyte-specific deletion of autophagy-related 5 (Atg5) leads to glomerulopathy in aging mice and this was associated with ER stress, podocyte loss, proteinuria and glomerulosclerosis." (PMID 26239352, 2015). "Genetic ablation of the core autophagy gene autophagy-related 5 (Atg5) in podocytes induces proteinuria and accelerates glomerulosclerosis." (PMID 41009719, 2025). "For instance, the deletion of Atg5 in the podocytes led to glomerulosclerosis, proteinuria, and other abnormalities typical for the aging kidney, e.g., lipofuscin accumulation, the presence of damaged mitochondria, and oxidize or ubiquitinated proteins." (PMID 30360430, 2018). "Similarly, podocyte-specific knockout of Atg5 (autophagy related-5), a ubiquitin ligase involved in autophagy, resulted in increased oxidative stress, podocyte injury, glomerulosclerosis and proteinuria." (PMID 40342933, 2025). "Some researchers found that the weakened autophagy function in podocytes caused the accumulation of oxidized proteins, endoplasmic reticulum stress, and proteinuria, eventually leading to podocyte damage and glomerular sclerosis in a mouse model through knocking out the autophagy-related gene Atg5." (PMID 32047576, 2020). "In vivo experiments showed that specific knockout of the autophagy protein 5 (Atg5) gene, an important component of autophagy, leads to increased proteinuria and upregulation of oxidative stress in older rats, resulting in glomerulosclerosis, TEC damage and apoptosis." (PMID 31925859, 2020). "Mice with podocyte-specific deletion of the autophagy-related gene Atg5 exhibit reduced autophagic activity in podocytes, concomitant with the accumulation of oxidized protein, endoplasmic reticulum stress, and proteinuria, which eventually leads to podocyte injury and glomerulosclerosis." (PMID 33881140, 2021). "Podocytes rely on basal autophagy, and mice lacking the autophagy protein 5 (ATG5) gene in podocytes show increased albuminuria, podocyte loss, and glomerulosclerosis." (PMID 39941397, 2025).